MDM2 (MDM2 proto-oncogene)
Diseases named in the same sentence as MDM2 in open-access papers (continued):
Sharing a sentence is not in itself a finding about the gene and the disease.
tumor (continued). "We observed a similar trend for other genes and while we found MDM2 to be up-regulated in most tumours, the overall senescence pathway was dampened." (PMID 28387377, 2017). "In a study comprising approximately 4000 biopsies obtained from clinical or xenograft tumors across 28 tumor types, the frequency of MDM2 amplifications varied over a wide range in different types of cancer." (PMID 27888811, 2017). "WDLPS/DDLPS is the most frequent subtype of STS, and these tumours are characterized by a specific amplification of MDM2 (12q14-15)." (PMID 28629371, 2017).
tumor (continued). "Tumor cells displayed overexpression of MDM2, CDK4, and P16 by immunohistochemistry and CGH revealed amplification of 12q13-15 as the only genetic imbalance." (PMID 28377828, 2017). "To validate the mechanisms of estradiol in vivo, we assessed the expression of hnRNPA1 and MDM2 of tumor tissues at protein levels." (PMID 28035066, 2017). "3G5 is not able to enter cells, but linking its variable fragment to that of the cell-penetrating 3E10 creates a bispecific antibody that can successfully inhibit MDM2, leading to cell growth arrest in vitro and reduction of tumor growth in vivo." (PMID 26907261, 2016). "These include the oncogene MDM2 and various genes supporting cell proliferation (KI-67), apoptosis (Bax), tumor invasion and metastasis (MMP9) and tumor angiogenesis (VEGF), as well as the anti-apoptosis gene BCL-2." (PMID 26943040, 2016). "The anti-tumor activities of MDM2 siRNA and the MDM2 inhibitor RG7112 were assessed by cell viability assay, western blotting, and flow cytometry." (PMID 27659536, 2016). "Several proteins such as fibromodulin, CD229, MDM2, and CD23 have been recognized as tumor-associated antigens in CLL." (PMID 27302925, 2016). "MDM2 expression and Akt activity (phosphorylated Akt/total Akt) in tumor tissue were studied by Western blot assay." (PMID 27004407, 2016). "The inhibitory effect of triptolide on MDM2-mediated Akt activation was eliminated in tumor cells with MDM2 overexpression." (PMID 27004407, 2016). "In particular, cytological amplification analysis of ALT/DDLPS-related marker MDM2 of the cells isolated from the tumor specimen corroborated the presence of cancer cells." (PMID 27918490, 2016).
tumor (continued). "One CDK4 amplified tumor with grey-zone MDM2 amplification showed only a low HMGA2 copy number increase." (PMID 27662657, 2016). "Upon review of the original resection specimen, we were able to show that the tumor demonstrated MDM2 amplification." (PMID 26987706, 2016). "We thus computed the correlation score between changed MDM2 expression level and changed MDM2 RNA editing levels for each site in each tumor type." (PMID 26980570, 2016). "As expected, marked PARP and cleaved caspase-8 positive staining was observed in the MDM2 knockdown xenograft tumor, while lower expressions of PARP and cleaved caspase-8 were found in G5-DAT62/siScr treated tumor." (PMID 27259273, 2016). "All of them had sub-nanomolar affinity to MDM2, good pharmakokinetic properties, tumour suppression and are currently in different phases of clinical trial." (PMID 26936767, 2016).
tumor (continued). "Six miRNAs with p<0.01 were increased, whereas the remaining were decreased in MDM2-expression positive tumours." (PMID 26918730, 2016). "Although also encoded by the CDKN2A gene, p14ARF utilizes a completely different reading frame with distinct tumour suppression functions by inhibiting MDM2 and activating p5325." (PMID 26104880, 2015). "Patients characterized as homozygous G/G mdm2 SNP309 often have accelerated tumor formation, earlier age of cancer onset and increased incidence of multiple types of cancers." (PMID 26416444, 2015). "Many, including us, have compared RASSF1A and RASSF6 in their properties as a tumor suppressor, their ability to interact with MDM2, their involvement in TNF-α signaling and inflammation, as well as comparing them with Nore1- in the Ras-induced apoptosis." (PMID 26690221, 2015). "The aim of this study was to investigate the expression levels of MDM2 and HIF1alpha in tumour samples from chemonaive MPM patients, testing different expression levels in the different histologic subtypes." (PMID 26544728, 2015). "We investigated the utility of assessment of MDM2 amplification by FISH as an ancillary tool for the histological diagnosis of WDL and DDL and in distinguishing these tumors from other neoplasms in their differential diagnosis in routine diagnostic practice." (PMID 25810689, 2015). "The significant downregulation of MDM2 expression levels by JapA has been observed in these tumor samples." (PMID 26461225, 2015). "Our data thus show that SJSA-1 tumor cells acquire very different levels of resistance in vitro and in vivo to the MDM2 inhibitor SAR405838." (PMID 26070072, 2015). "As a first step towards identifying the determinants of sensitivity to MDM2 inhibition, a panel of 260 human tumor cell lines of diverse tissue origins was screened in a 72-hour cell proliferation assay." (PMID 25730903, 2015).
tumor (continued). "The in vivo inhibition of MDM2 and increase in apoptosis in tumor tissues were further confirmed by an immunohistochemical analysis." (PMID 26041888, 2015). "We found that RAD6 protein levels decreased mostly in the cancer samples compared with the pericarcinous tissue, while the ASF1A, H3K56Ac and MDM2 levels increased significantly in most of the tumor samples." (PMID 26336826, 2015). "Applying this cutoff across all tumor samples within TCGA resulted in a pan-cancer MDM2 amplification rate far lower than previously published." (PMID 25730903, 2015). "In particular, overexpression of MDM2 was shown to be essential in promoting both the entry into cell cycle and tumor cell survival in myeloma cells." (PMID 25028664, 2014). "The fact that both MDM2 amplification and the fusion genes are found in both the primary tumor and metastasis indicate, however, that both play a role in tumorigenesis." (PMID 25176350, 2014). "In a second tumour (OESO_0384), evidence of DM arising from a chromothriptic event involving four chromosomes harboured MDM2 gene was identified and similarly verified using PCR and FISH." (PMID 25351503, 2014).